PPM1L (protein phosphatase, Mg2+/Mn2+ dependent 1L)
Description:
Acts as a suppressor of the SAPK signaling pathways by associating with and dephosphorylating MAP3K7/TAK1 and MAP3K5, and by attenuating the association between MAP3K7/TAK1 and MAP2K4 or MAP2K6.
Synonyms: PP2C-epsilon; PP2CE; PPM1-LIKE
Tractability: Antibody: UniProt predicts a signal peptide or a membrane-spanning region. PROTAC: ubiquitination databases record sites on it; its protein half-life has been measured.
Gene: Protein-coding gene on chromosome 3 (160,755,602 to 161,078,902, forward strand). Ensembl gene ENSG00000163590.
Subcellular location: Membrane
Subcellular location (Human Protein Atlas): Cytosol; Nucleoplasm
Pathways (Reactome):
Metabolism: Sphingolipid de novo biosynthesis
Gene Ontology:
Molecular function: protein serine/threonine phosphatase activity; cation binding
Biological process: sphingolipid biosynthetic process
Cellular component: extracellular exosome; endoplasmic reticulum membrane; membrane
Genetic constraint (gnomAD): Loss-of-function variants: 13 observed, 33.1 expected, observed/expected ratio (o/e) 0.39, 90% interval 0.25 to 0.62. The upper end of that interval is the gene's LOEUF score, 0.62, which puts it in group 2 of 6, group 1 being the genes least tolerant of losing a copy. Missense variants: 326 observed, 477.54 expected, observed/expected ratio (o/e) 0.68, 90% interval 0.62 to 0.75. Synonymous variants: 184 observed, 187.52 expected, observed/expected ratio (o/e) 0.98, 90% interval 0.87 to 1.11.
Homologues: Orthologues: chimpanzee PPM1L (100% identical), dog PPM1L (99% identical), macaque PPM1L (99% identical), guinea pig PPM1L (99% identical), rat Ppm1l (99% identical), mouse Ppm1l (99% identical), pig PPM1L (99% identical), rabbit PPM1L (99% identical), tropical clawed frog ppm1l (93% identical), zebrafish ppm1la (89% identical), zebrafish ppm1lb (68% identical), Drosophila melanogaster CG7115 (45% identical). Paralogues in human: PPM1K (31% identical), PPM1E (26% identical), ILKAP (26% identical), PPM1F (25% identical), PPM1G (25% identical), PPM1B (24% identical), PDP2 (24% identical), PPM1N (24% identical), PPM1A (23% identical), PPM1H (23% identical), PP2D1 (22% identical), PPM1M (22% identical), and 4 more.
Diseases named in the same sentence as PPM1L in open-access papers:
PPM1L is named in the same sentence as 11 diseases in open-access papers, as found by Europe PMC text mining. Sharing a sentence is not in itself a finding about the gene and the disease. The quoted sentences say what the papers report.
metabolic syndrome (3 papers, 2012 to 2024). A cluster of metabolic risk factors for CARDIOVASCULAR DISEASES and TYPE 2 DIABETES MELLITUS. "In fact, the gene coding for PP2Ce, ppm1l, was first identified as candidate disease-causing gene for complex traits associated with metabolic syndrome." (PMID 25369058, 2014). "PPM1L has previously been linked to traits associated with the metabolic syndrome." (PMID 39623445, 2024). "Network and/or module based approaches also proved to be powerful in pinpointing disease causing genes, many of which, for example Ppm1l for metabolic syndrome or TBC1D16 and RAB27A for melanoma, have been confirmed experimentally while others are supported by literature evidences." (PMID 23755063, 2012).
Obesity (2 papers, 2021 to 2024). Accumulation of substantial excess body fat. "The macrophage-enriched network has a causal correlation with metabolic disease traits, which involved three obesity genes (including PPM1L)." (PMID 33526014, 2021).
familial colorectal cancer (1 paper, 2013). Familial colon cancer is a cluster of colon cancer within a family. "This region contains an element that regulates the expression of an upstream candidate tumor suppressor, PPM1L, thus providing a novel mechanism for colorectal tumorigenesis in APC mutation-negative familial colorectal cancer." (PMID 23258604, 2013).
gastric cancer (1 paper, 2022). A primary or metastatic malignant neoplasm involving the stomach. "According to our GSE54129 dataset, the expression level of BPTF was increased in gastric cancer and furthermore, BPTF formed DRLs with PPM1L, NKX6.3 and PIK3R3." (PMID 35421923, 2022).
prostate carcinoma (1 paper, 2016). A carcinoma that arises from epithelial cells of the prostate gland. "In addition, although the number and function of downregulated genes seemed to be less relevant than those upregulated, however we have identified that some of them also appear downregulated in prostate cancer (DST; VAV3; PLK3HH2; ITG6B; PPM1L)." (PMID 27732959, 2016).
schizophrenia (1 paper, 2024). A major psychotic disorder characterized by abnormalities in the perception or expression of reality. "While no prior studies have identified specific roles of PPM1L and KLHL8 in schizophrenia, our data nominate PPM1L and KLHL8 as potential regulators of MAP2 phosphorylation levels, and thus as novel targets for further exploration to reverse schizophrenia-related hyperphosphorylation of MAP2." (PMID 39532265, 2024). "Interestingly, novel gain-of-function interactions with PPM1L and KLHL8 nominated these as regulators of phosphoS1782 MAP2 abundance and potential therapeutic targets in schizophrenia." (PMID 39532265, 2024).
tumor (6 papers, 2019 to 2023). "Our findings suggest that circFAM120B is a promising biomarker of ESCC, which acts as a tumor suppressor via the circFAM120B/miR-661/PPM1L axis and PKR/p38 MAPK/EMT pathway, supporting its significance as a candidate therapeutic target." (PMID 35436983, 2022). "Previous studies indicated that PPM1L was a tumor suppressor in colorectal tumorigenesis via negatively regulating TGF-β and BMP signaling pathways." (PMID 35436983, 2022). "Mechanistically, circFAM120B was predominantly located in the cytoplasm, guarantying its sponging for miR-661 to restore the expression of PPM1L, a tumor suppressor." (PMID 35436983, 2022). "Our bioinformatics analysis based on GSE131969 and data from 96 pairs of ESCC tissues showed a downregulation trend of PPM1L, consistent with its potential function as a tumor suppressor in ESCC." (PMID 35436983, 2022). "A series of rescue experiments were designed to elucidate whether circFAM120B regulates tumor progression via this newly identified circFAM120B/miR-661/PPM1L axis." (PMID 35436983, 2022). "CircFAM120B acts as a sponge for miR-661, which targets the tumor-suppressor gene PPM1L." (PMID 35884948, 2022). "In addition, five other genes, including TBPL1, USP28, NRG3, PPM1L, and RGR, were regulated by eRNAs expressed only in LGG tumor tissue; whereas SEMA4G was regulated by LGG-specific seRNAs." (PMID 35299740, 2022).
cancer (2 papers, 2022 to 2023). A tumor composed of atypical neoplastic, often pleomorphic cells that invade other tissues. "The positive regulation of PPM1L by BPTF was lost from normal to cancer, and meanwhile the expression of PPM1L was found to be decreased in cancer, which is consistent with the regulation change." (PMID 35421923, 2022). "A total of 20 target mRNAs of three miRNAs were predicted, among which seven target mRNAs—ASAP3, BCL2L2, LMF1, PPM1L, PTPN21, SLC18A2, and NR3C2—had prognostic value; PRKACB, PDCD4, RPS6KA5, and BCL2L2 were enriched in the miRNA cancer pathway." (PMID 36829221, 2023). "Among these mRNAs, the prognostic values and mechanisms of LMF1, PPM1L, and PTPN21 have rarely been reported in cancers." (PMID 36829221, 2023).
PPM1L also shares sentences with these, for which no sentence is quoted: esophageal squamous cell carcinoma (1 paper); melanoma (1); metabolic disease (1).